TSC2 (TSC complex subunit 2)
Diseases named in the same sentence as TSC2 in open-access papers (continued):
Sharing a sentence is not in itself a finding about the gene and the disease.
tuberous sclerosis (continued). "The first full‐length human TSC2 cDNA reported was from human fetal brain and included exon 25, but not exon 31 [European Chromosome 16 Tuberous Sclerosis Consortium, 1993]." (PMID 26703369, 2016). "The pathological basis of LAM is associated with Tuberous Sclerosis Complex (TSC), a multi-system disorder marked by low-grade tumors in the brain, kidneys, heart, eyes, lung and skin, arising from inherited or spontaneous germ-line mutations in either of the TSC1 or TSC2 genes." (PMID 25505789, 2014). "PEComas may be associated with the tuberous sclerosis complex (TSC), an autosomal dominant neurocutaneous disorder caused by genetic alterations of the TSC1 (9q34) or TSC2 (16p13.3) genes, and characterized by mental retardation, seizures and multiple tumors in different sites." (PMID 24575738, 2014). "The importance of TSC1/TSC2 in the control of mTORC1 is revealed in tuberous sclerosis patients, where functional loss of either TSC1 or TSC2 results in non-metastatic tumors (reviewed in 10)." (PMID 24303063, 2013). "Tuberous sclerosis genes, hamartin (TSC1) and tuberin (TSC2) are involved in this pathway." (PMID 21283628, 2011). "The prevailing theory suggests the involvement of TSC1/TSC2 genes and sex hormones in its pathogenesis, yet the emergence of cases in females and those without tuberous sclerosis contradicts this hypothesis." (PMID 38989358, 2024). "However, given the absence of clinical evidence for tuberous sclerosis and NGS revealing no mutations in TSC1 or TSC2, the PDs for these two cases were glioma, NEC." (PMID 37998600, 2023). "Similarly, we identified a TSC2 variant in all tumours from a patient in whom no NF2 mutations were found and without known tuberous sclerosis (TS)." (PMID 36882706, 2023). "Tuberous sclerosis complex is an autosomal dominant disorder characterized by benign tumors arising from the abnormal activation of mTOR signaling in cells lacking TSC1 (hamartin) or TSC2 (tuberin) activity." (PMID 29343513, 2018). "Moreover, polymorphic and non-pathogenicvariants in the TSC1 and TSC2 genes can act asphenotype modifiers in tuberous sclerosis, and they need to be further explored." (PMID 28222202, 2017). "We previously showed that early post-natal immune activation induces hippocampal-dependent social memory deficits in a male, but not in a female, mouse model of tuberous sclerosis complex (TSC; Tsc2+/− mice)." (PMID 38255309, 2024). "These lesions can occur in patients with or without Tuberous Sclerosis Complex (TSC) and are driven by mutations in the TSC1 and TSC2 genes, which encode for hamartin and tuberin." (PMID 39410016, 2024). "Here, we report a patient with a clinical diagnosis of Tuberous sclerosis, combined with unusual secondary features, but negative clinical tests including TSC1 and TSC2." (PMID 38253421, 2024). "DDIT4 positively regulates the activity of the Tuberous Sclerosis (TSC) complex (TSC1, TSC2 and TBC1D7), which in turn acts as a crucial negative regulator for the mTORC1 activity." (PMID 36674750, 2023). "Moreover, in the renal tumours from mouse models of tuberous sclerosis complex (TSC), the absence of Tsc2 inhibits FLCN and thus promotes RagC/DGTP formation, establishing a non‐canonical means of preventing mTORC1‐mediated phosphorylation of TFEB, thereby driving its nuclear translocation." (PMID 37728021, 2023).
epilepsy (96 papers, 2010 to 2026). A brain disorder characterized by episodes of abnormally increased neuronal discharge resulting in transient episodes of sensory or motor neurological dysfunction, or psychic dysfunction. "In conclusion, deletion of Tsc2 from neurons in a focal region of the cortex is sufficient to cause epilepsy." (PMID 41255962, 2025). "For example, mutations in the TSC2 gene have been associated with earlier onset of epilepsy and epilepsy accompanied by intellectual deficits." (PMID 40364023, 2025). "One study specifically reported the proportions of patients with epilepsy as being 86% for patients with TSC2 mutations, but only 35% for patients with TSC1 mutations." (PMID 41291828, 2025). "A focal, postnatal deletion of Tsc2 from cortical neurons is sufficient to cause both epilepsy and behavioral deficits in mice." (PMID 41255962, 2025). "Pathogenic variants in TSC1 and TSC2 lead to mTORC1 hyperactivation, producing benign tumours in multiple organs, including the brain and kidneys, and drug-resistant epilepsy, a typical sign of TSC." (PMID 39334956, 2024). "Heterozygotic Tsc2 mutations are the most prevalent and the most frequently associated with severe clinical manifestations such as epilepsy." (PMID 39010669, 2024). "Some examples that have been described in the literature include the occurrence of TSC2 variants and earlier onset of epilepsy, and epilepsy with an intellectual deficit." (PMID 38373162, 2024). "TSC is a rare genetic disorder caused heterozygous mutations in either the Tsc1 or Tsc2 genes, typically leading to serious neurologic comorbidities, such as severe epilepsy." (PMID 39010669, 2024). "TSC2 variations were identified in 8.5% of patients and were predominantly linked to earlier epilepsy onset and a higher prevalence of DD/ID, consistent with prior studies reporting TSC2 variations in 6%–10% of pediatric epilepsy cohorts." (PMID 39906551, 2024). "Of note, epilepsy onset occurred later in life in our patients with TSC1 variants than patients with TSC2 variants (3.2 years vs. 0.6 years, respectively)." (PMID 37946245, 2023). "Previous studies similarly reported a higher frequency of epilepsy in general, infantile spasms, and refractory focal epilepsy in patients with TSC2 compared with TSC1 variants." (PMID 37946245, 2023). "The most frequent NDDs burdening TSC patients are ID and ASD, which affect 50% of individuals and share common risk factors including the presence of TSC2 mutation, structural brain abnormalities and epilepsy." (PMID 35440050, 2022). "Mutations in regulators of mTORC1, such as Tsc1 and Tsc2, lead to neurodevelopmental disorders associated with autism, intellectual disabilities and epilepsy." (PMID 34135323, 2021). "Tuberous sclerosis complex (TSC) is a congenital disorder characterized by cortical malformations and concomitant epilepsy caused by loss‐of‐function mutations in the mTOR suppressors TSC1 or TSC2." (PMID 33786950, 2021). "This syndrome is caused by mutations in TSC1 or TSC2, resulting in epilepsy, cognitive disfunction and behavioral abnormalities." (PMID 34820379, 2021). "Genetic data were available for 849 individuals with epilepsy; 587 (69.1%) had pathogenic mutations in the TSC2 gene, while 155 (18.3%) had mutations in the TSC1 gene." (PMID 34566842, 2021). "Tsc1+/- and Tsc2+/- mutations are known to induce epilepsy in humans, but so far, a spontaneous epilepsy phenotype has not been described in the Tsc2+/- rat or any comparable pre-clinical mouse models." (PMID 33863288, 2021). "TSC2 mutation, epilepsy, seizure before 2 years old, course of epilepsy (more than 2 years), HRSF, multiple antiepileptic drugs (≥2), ID, and TANDs were closely related to poor QOL." (PMID 33225634, 2021). "TSC2 mutation, epilepsy, early onset, long disease course and HRSF, ID, and TANDs are risk factors for poor QOL." (PMID 33225634, 2021).
epilepsy (continued). "Compared with individuals with TSC1 pathogenic variants, NMI patients had more retinal hamartomas (p = 0.035), and compared with individuals with TSC2 pathogenic variants, they had less epilepsy (p = 0.003) and fewer subependymal nodules (SENs) (p = 0.004)." (PMID 32211034, 2020). "Compared with patients with TSC1 variants, NMI patients exhibited more retinal hamartomas (p = 0.035), were less likely to have epilepsy (p = 0.003), and had fewer cortical tubers (p = 0.013) and SENs (p = 0.004) than patients with TSC2 variants." (PMID 32211034, 2020). "Specifically, TSC2 pathogenic variants have been associated with a significantly higher occurrence of IS and other epilepsy types." (PMID 32216820, 2020). "Individuals with TSC2 mutation were also more likely to have epilepsy onset at less than two years of age, as well as infantile spasms." (PMID 33281431, 2020). "Compared with TSC1 patients and NMI patients, those with TSC2 variants have a greater chance of developing renal abnormalities, intracranial lesions, and skin diseases, and their age at the onset of epilepsy is younger." (PMID 32211034, 2020). "In the present study, we found that mTOR hyperactivation resulting from loss of Tsc2 in Mitf-M-derived cell lineage was associated with the development of typical epilepsy, mitochondria hyperproliferation, and aberrant intracellular calcium dynamics." (PMID 31978189, 2020). "Tuberous sclerosis complex (TSC) is a neurodevelopmental disorder caused by deletions in the TSC1 or TSC2 genes that is associated with epilepsy in up to 90% of patients." (PMID 31761686, 2019). "Instead, most APEs with P/LPs of neurodevelopment-associated epilepsy genes such as TSC2 or RELN, or with structural brain lesions, were multi-drug resistant." (PMID 31875159, 2019). "An encouraging example of a successful individualized approach has recently been reported, demonstrating improvement of ASD symptoms and epilepsy in an individual with TSC2 mutations after treatment with everolimus." (PMID 28472301, 2017). "Various pre-clinical and clinical studies demonstrated that loss of function mutations of the genes encoding for the natural mTOR inhibitors TSC1 and TSC2 lead to aberrant mTOR signaling with consecutive development of cortical malformations and epilepsy." (PMID 27809914, 2016). "For example, a role for the TSC2 c.2859dup (p.K954Qfs*6) and c.3846_3855delinsG (p.S1282_G1285delinsR) variants in epilepsy cannot be excluded." (PMID 26703369, 2016). "Tuberous sclerosis complex (TSC) is caused by loss of function of TSC1 and TSC2 genes, and courses with presence of cortical tubers, mental retardation, autistic-like behavior and epilepsy." (PMID 24904277, 2014). "TSC2 mutations have been associated with abnormal cell growth, intellectual disabilities, and neuropsychological disorders in patients, with 80%–90% having epilepsy." (PMID 41255962, 2025). "TSC2 mutations were more prevalent than TSC1 mutations in people with TSC-associated epilepsy." (PMID 41291828, 2025). "Here we show that focal lesions containing TSC2 KO cells are sufficient to cause epilepsy." (PMID 41255962, 2025). "Likewise, the surgical outcomes of epilepsy are less responsive in those with TSC2 compared with TSC1 variants." (PMID 38540392, 2024). "TSC2 is linked to neurological deficits like epilepsy, autism, and intellectual disabilities." (PMID 37628788, 2023). "Epilepsy generally exhibits an earlier onset and is also more severe as a result of TSC2 mutations." (PMID 35883484, 2022). "TSC is an autosomal dominant genetic syndrome caused by inactivating mutations of TSC1 (hamartin gene) and TSC2 (tuberin gene), characterized by the development of PEComas along with hamartomas, giant cell astrocytomas, and neurologic dysfunction including epilepsy or intellectual disability." (PMID 34442003, 2021).
epilepsy (continued). "In addition, TSC2 mutation, epilepsy, seizure before 2 years old, and course of epilepsy ≥ 2 years were also related to lower psychosocial health scores, but not to physical health scores." (PMID 33225634, 2021). "Simple linear regression revealed that TSC2 mutation, epilepsy, seizure before 2 years old, course of epilepsy, HRSF, multiple antiepileptic drugs, ID, and TANDs could be associated with poor QOL." (PMID 33225634, 2021). "In clinical contexts, it remains unclear whether epilepsy in TSC patients is attributable to the Tsc2+/- mutation, is secondary to cortical tubers acting as epileptogenic foci or may be a combination of both." (PMID 33863288, 2021). "Epilepsy was seen in 88% of patients and was more frequent in individuals with a TSC2 mutation." (PMID 33281431, 2020). "Risk factors for ASD are epilepsy, infantile spams, and mutations in TSC2." (PMID 26631248, 2015). "Furthermore, TSC2 pathogenic variant carriers are at greater risk for renal malignancies, cardiac rhabdomyomas, intellectual disability, infantile epileptic spasms, and drug-resistant epilepsy." (PMID 38540392, 2024). "Accordingly, data on ASD and epilepsy, mostly obtained in males, reported the same alterations that we observed in Tsc2+/− males." (PMID 40691437, 2025). "Disruption of mTOR signaling due to variants in its repressors such as TSC1, TSC2, DEPDC5, PTEN or in its activators such as RHEB, and MTOR lead to a set of disorders characterized by early onset and often drug-resistant epilepsies called mTORopathies." (PMID 40792287, 2025). "The cohort from another epilepsy center (n = 23) has a TSC1:TSC2 ratio of 1:1.4 (9:13) and more familial cases." (PMID 39596632, 2024). "We reported the case of an infant girl with TSC2/PKD1 contiguous gene syndrome manifesting as epilepsy and early-onset polycystic kidney lesions." (PMID 39323690, 2024). "And so, our study suggested that induced models of epilepsy/seizures in Tsc2+/− mice can be used to study some aspects involving epilepsy for this disorder." (PMID 39010669, 2024). "Comorbidity of epilepsy and autism in tuberous sclerosis complex 2 (TSC2) is very frequent, but the link between these conditions is still poorly understood." (PMID 39010669, 2024). "The frequency, severity, and age of onset of epilepsy is also higher and younger in TSC2 patients, and these findings have been replicated in mouse models." (PMID 38540392, 2024). "In summary, our results validate that Tsc2+/− mice are more vulnerable to display seizures after an acute administration of a proconvulsant drug and support the use of the TSC2 mouse model in future TSC‐related induced epilepsy research." (PMID 39010669, 2024). "Different experimental studies have demonstrated that pathogenic mutations in TSC1 or TSC2 can lead to overactivation of mTORC1, resulting in altered neuronal intrinsic excitability (hyperexcitation/hypoexcitation) and/or synaptic transmission disorders, which may be the basis for epilepsy onset." (PMID 38966089, 2024). "In epilepsies caused by alterations in mTOR pathway genes, such as DEPDC5, TSC1, or TSC2, the drug rapamycin can be used to manage symptoms as it inhibits mTOR pathway." (PMID 37834053, 2023). "Mutations in the mTOR-inhibiting (e.g., tuberous sclerosis TSC1, TSC2 and GATOR1 complex) genes are particularly strongly linked to epilepsy." (PMID 36982355, 2023). "In our cohort, one patient received a dual diagnosis of epilepsy with both a documented alteration in the TSC2 gene and a substantial deletion within the long arm of chromosome 18." (PMID 38328757, 2023). "In a mouse model, conditional knockout (CKO) of TSC2 in GFAP-positive cells also produces a more severe epilepsy phenotype than TSC1 CKO." (PMID 35883484, 2022). "75% of TSC1 patients and 81% of TSC2 patients experienced epilepsy in the form of a range of seizure types." (PMID 35440050, 2022).
epilepsy (continued). "The proportion of patients with incompletely controlled epilepsy (score 3, having active seizures) was higher in TSC2, and the difference was significant in age ≥10 years." (PMID 36232477, 2022). "The most common cause of epilepsy was genetic, including patients with findings in chromosomal microarray tests or mutations in specific genes (CDKL5, TSC2, etc.)." (PMID 36203978, 2022). "An ASD-like phenotype was previously reported in both epilepsy-naive Tsc2+/- (Eker) rats and wild-type rats after kainic acid-induced DSE." (PMID 33863288, 2021). "Because individuals with TSC2 mutations tend to be more severely affected, especially by neuropsychiatric manifestations and epilepsy, an even higher COI can be presumed among populations with higher shares of TSC2 mutations." (PMID 34078440, 2021). "Tuberous sclerosis complex is a multisystem disorder caused by mutations in mechanistic target of rapamycin regulators TSC1 or TSC2, with prominent neurological manifestations including epilepsy, focal cortical dysplasia and neuropsychiatric disorders." (PMID 34632383, 2021). "Mutations in TSC1 or TSC2 genes cause tuberous sclerosis complex (TSC), a disorder associated with epilepsy, autism, and intellectual disability." (PMID 32375878, 2020). "Neurodevelopment-associated epilepsy genes, such as TSC2 or RELN, or structural brain lesions were more strongly associated with epilepsy pharmacoresistance." (PMID 31875159, 2019). "Instead, neurodevelopment-associated epilepsy genes, such as TSC2 or RELN, or structural brain lesions were more strongly associated with epilepsy pharmacoresistance." (PMID 31875159, 2019). "Astroglia-specific deletion of Tsc1 or Tsc2 resulted in increased glial proliferation accompanied by epilepsy and premature death." (PMID 26693177, 2015). "Animal models deleting PTEN, TSC1, and TSC2 consistently produce epilepsy phenotypes, demonstrating that increased mTOR signaling can provoke neuronal hyperexcitability." (PMID 24672426, 2014). "Animal studies show that the TSC2 gene mutation is a more common cause of severe phenotypic features, including neurological symptoms, including epilepsy, and patients with PKD (polycystic kidney disease) and TSC2 mutations are more often exposed to early symptoms of polycystic kidney disease." (PMID 39410026, 2024). "Our data, as well as recent work correcting PI3K-dependent or TSC2-dependent epilepsies with more targeted drugs, imply that direct correction of a hyperactive node may be more effective than the simple use of rapalogs for all mTOR pathway disorders." (PMID 37741456, 2023). "It is believed that heterozygous mutation of Tsc1 or Tsc2 results in the onset of TSC in humans; however, heterozygous knockout of Tsc1 or Tsc2 did not cause hamartoma formation or epilepsy in a mouse model." (PMID 36606143, 2022). "Moreover, the prevalence of epilepsy in TSC2 patients was lower than in the TOSCA study, which indicated that TSC2 patients with milder central nervous system symptoms were diagnosed more frequently in Japan." (PMID 36232477, 2022). "Although this study suggests that TSC1 patients may have a higher remission rate than TSC2 patients, it remains a possibility that a more detailed analysis could prove TSC2 patients have more severe epilepsy." (PMID 36232477, 2022). "For instance, TSC2 mutations were more common than TSC1 mutations and the prevalence of certain disease features such as cortical tubers, subependymal nodules and epilepsy were similar to previous reports." (PMID 28057044, 2017). "The exon 5 and exon 31 variants (TSC2 c.569dup and TSC2 c.3846_3855delinsG) are both inherited from a parent who also has clinical TSC (hypomelanotic macules, facial angiofibromas, cortical tubers, epilepsy, intellectual disability, and renal angiomyolipomas)." (PMID 26703369, 2016). "Risk factors for ASD in these patients are epilepsy, infantile spams, and mutations in TSC2, while the localization of tubers is not correlated to it." (PMID 26631248, 2015).